IL6 (interleukin 6)
Diseases named in the same sentence as IL6 in open-access papers (continued):
Sharing a sentence is not in itself a finding about the gene and the disease.
COVID-19 (continued). "Several studies reported elevation of serum IL-6 and IL-10 in COVID-19 patients, and this elevation was dramatic with severe COVID-19 due to hyperactivation of the humoral immune system." (PMID 41203712, 2025). "This meta-analysis underscores the potential of IL-6, IL-10, and S100 proteins as important biomarkers in evaluating COVID-19 severity, offering valuable insights to help clinical management." (PMID 41585373, 2025). "Numerous laboratory markers, including neutrophils, lymphocytes, CRP, procalcitonin (PCT), and IL‐6, have been reported to be related to the morbidity and mortality of COVID-19." (PMID 41309368, 2025). "Each patient initially presented with varying degrees of frailty, elevated IL-6 levels, and respiratory symptoms typical of COVID-19." (PMID 41020118, 2025). "We found that IL-6, IL-10, IL-6/IL-10 ratio, and miR-155 expression levels were significantly higher in COVID-19 patients than in healthy controls (p-values < 0.001)." (PMID 41203712, 2025). "Biochemical and hematological parameters, such as neutrophil count, lymphocyte count, neutrophil/lymphocyte ratio, CRP, interleukin-6, D-dimer, troponin-I, ferritin, and creatine kinase, were investigated as prognostic indicators for individuals with COVID-19." (PMID 40142738, 2025). "An 8-week exercise intervention in COVID-19 survivors has also been shown to reduce pro-inflammatory markers such as IL-6 and fibrinogen, alongside improvements in physical performance." (PMID 40943540, 2025). "Our results revealed that serum from patients with severe COVID-19 significantly upregulated IL6 and IL12A expression in HUVEC within 60 min of stimulation." (PMID 41583455, 2025). "Creatinine, D-dimer, and CRP were in positive correlation with clinical outcome of male COVID-19 and IL-6." (PMID 40868247, 2025). "This study aims to address this gap by investigating the association between thirteen functional variants in IL1B, IL6, and TNF and severe COVID-19 outcomes in 500 unvaccinated individuals from southern Brazil." (PMID 40506975, 2025). "One important possible mechanism is the cytokine storm and abnormally high levels of inflammatory mediators, such as C-reactive protein, tumor necrosis factor-alpha, and IL-6, seen in COVID-19 patients." (PMID 41002604, 2025). "The current work showed that ROC curve analysis of IL-6 and IL-17 showed the high specificity and moderate sensitivity of both tests in COVID-19 patients." (PMID 41184328, 2025). "Altogether, these findings open a new strategy therapy for COVID-19.Adjuvant immune therapy for COVID-19 has usually been focused on blockinghyperinflammation (e.g., corticosteroids, IL-6 inhibitors, JAK inhibitors), asrecommended by WHO guidelines." (PMID 41259458, 2025). "Our findings identify elevated IL-17 and IL-6 levels as key inflammatory biomarkers directly predictive of COVID-19 severity and clinical outcomes." (PMID 41184328, 2025). "In severe COVID-19 patients, IL-6 signaling regulates PAI-1 production, forming a positive feedback loop that exacerbates systemic inflammation and circulatory deterioration, which can be mitigated by blocking the IL-6 receptor." (PMID 40007559, 2025). "Natural substances such as flavanone derivatives have also been investigated, as it has been seen that they have immunomodulatory effects; in the COVID-19 setting, they can reverse the cytokine storm by inhibiting IL-6." (PMID 40332501, 2025). "The Dublin-Boston score (DBS) is a biomarker that captures the four-day change in IL-6:IL-10 and was shown to predict short-term clinical status in moderate-to-severely ill COVID-19 patients in the first week of hospitalization." (PMID 41322840, 2025). "Regarding interleukin-6 (IL-6) and procalcitonin, elevated values were more frequent in the COVID-19 subgroup, where extreme values were also recorded." (PMID 40427060, 2025).
COVID-19 (continued). "Reduced FMD values, indicative of endothelial dysfunction, have been inversely correlated with higher IL-6 levels in patients with severe COVID-19 requiring intensive care unit (ICU) admission." (PMID 40143236, 2025). "As expected, CRP showed a strong and highly significant association with IL6, confirming prior studies that have consistently demonstrated the IL6–CRP axis as a central pathway in COVID-19-related inflammation." (PMID 41373577, 2025). "IL-6 inhibitors, such as tocilizumab, have been studied in COVID-19, where IL-6 drives severe lung inflammation and multi-organ failure." (PMID 40453076, 2025). "These patients had elevated serum levels of the pro-inflammatory cytokine interleukin-6 (IL-6), a prognostic indicator of mortality in COVID-19 patients." (PMID 40573079, 2025). "COVID-19 has been shown to alter micronutrient levels through mechanisms like hypoxia and IL-6-mediated suppression of selenoprotein (Sel) expression, further impairing antioxidant defenses and increasing ROS generation." (PMID 39860053, 2025). "Elevated serum levels of IL-6 and CRP as inflammatory markers are associated with the severity of COVID-19 and can be used as a prognostic marker of the disease." (PMID 40978940, 2025). "IL-6 cytokine is debatable as progressive decline in IL-6 has been observed in Long COVID or in recovered COVID-19 patients and is therefore considered a marker of the acute phase of the disease." (PMID 39849406, 2025). "Those cases who had been hospitalized with COVID-19 showed higher levels of interleukin-6 (P = 0.01*) and the long pentraxin PTX3 (P = 0.012*) following infection, relative to controls." (PMID 39885359, 2025). "For these reason, numerous randomized clinical trials are currently underway to explore the effectiveness of biopharmaceutical drugs, such as, interleukin-6 inhibitors, interleukin-1 blockers, Janus kinase inhibitors, in COVID-19." (PMID 40410684, 2025). "Taken together, an early change in the IL-6:IL-10 axis, captured succinctly by DBS, complements WHO-CPS and enhances short-term risk stratification in moderate-to-severe COVID-19." (PMID 41322840, 2025). "Frailty is a key determinant of poor outcomes in COVID-19, often driven by immune dysregulation and persistent inflammation—particularly elevated IL-6 levels." (PMID 41020118, 2025). "The primary outcome was to challenge the IL-6/KL-6 ratio capacity to decipher the three COVID-19 ARDS phenotypes (H, I and L) defined on clinical, spirometric and radiologic grounds." (PMID 40397955, 2025). "These markers reflect the immune dysregulation and hyperinflammatory states that exists in severe COVID-19, confirming IL-6’s central role and extending attention to IL-10, IL-8, and S100B as complementary markers of disease severity." (PMID 41585373, 2025). "Among 39 patients with moderate-to-severe COVID-19 (24 declined by day four), the change in IL-6:IL-10 captured by the DBS strongly predicted short-term outcome." (PMID 41322840, 2025). "Moderate and severe COVID-19 patients showed the highest percentage of overlap with high levels of IL-10 and IL-6 and TNF-α (47 % and 58%, respectively)." (PMID 40508859, 2025). "In patients with COVID-19 and diabetes, the levels of pro-inflammatory cytokines such as IL-6 are significantly elevated." (PMID 39917294, 2025). "IL-6 is a pleiotropic cytokine widely recognized as a central driver and reliable biomarker of severe COVID-19, with elevated levels strongly correlating with disease severity and poor prognosis." (PMID 41176818, 2025). "It is worth noting that IL-6, as the core mediator of the inflammatory response mentioned earlier, is significantly elevated in severe COVID-19 patients." (PMID 41156098, 2025). "The aim of this work was to evaluate the associations of polymorphisms in the TNF-α, IL-6, IL-8, IL-10, CCL5 and CXCL6 genes with COVID-19 outcomes and with the serum levels of IFN-α, IFN-γ, TNF-α, IL-1Ra, IL-6, IL-7, IL-10, CCL2, CCL3, CXCL8, CXCL10 and GCSF." (PMID 40881695, 2025).
COVID-19 (continued). "Compared to healthy individuals, COVID-19 patients have higher levels of inflammatory cytokines, such as interleukin-6 (IL-6), IL-10, and tumor necrosis factor-α (TNF-α)." (PMID 40084335, 2025). "Several studies have found that increased levels of IL-6 were observed in patients with COVID-19 and that the levels correlate strongly with the severity of the disease." (PMID 40872607, 2025). "Our findings corroborate previous studies reporting anxiety (27.3%) and depression (39%) in hospitalized COVID-19 patients, with both conditions correlating with longer hospital stays and elevated inflammatory markers (D-dimer, IL-6, IL-10)." (PMID 40087795, 2025). "Concerning systemic immunity in COVID-19, clinical studies have shown a significant rise in pro-inflammatory cytokines and chemokines (IL-1β, IL-2, IL-6, IL-8, IL-15, IFN-γ, TNF, MCP-1), characterizing cytokine release syndrome (CRS) or cytokine storm." (PMID 40572294, 2025). "A previous retrospective study showed that COVID-19 patients exhibit different degrees of elevated levels of inflammatory factors, including IL-1β, IL-2, IL-6, IL-7, IL-8, and TNF-α." (PMID 40438117, 2025). "Initially, we assessed the expression of IL6, IL12A, and TNFA, which are key pro-inflammatory genes implicated in the cytokine storm associated with COVID-19." (PMID 41583455, 2025). "Taken as a whole, IL-6 and KL-6 are two prognostic biomarkers whose concentrations kinetics, taken independently, seem to evolve in an opposite way over the course of COVID-19 and among the two prevailing phenotypes." (PMID 40397955, 2025). "In conclusion, patients with COVID-19 in the ICU had higher levels of IL-6 and zinc compared to the other groups." (PMID 40756075, 2025). "In severe cases of COVID-19, endothelial cells in the lung’s blood vessels are further activated by elevated levels of pro-inflammatory cytokines (IL-1, IL-6 and TNF) and ferritin, exacerbating a vicious cycle of immunothrombosis." (PMID 40612950, 2025). "Our most significant findings include the association of double mutant alleles (AA) of rs4646140 and rs2074192 in the ace2 gene with decreased IL-6 and IL-2 expression levels respectively in TB-COVID-19 participants." (PMID 40196114, 2025). "The current study aimed to spotlight the interplay between miR-155 expression levels and inflammatory cytokines IL-6 and IL-10 with their derived ratio in the context of COVID-19 severity and mortality." (PMID 41203712, 2025). "This prompted us to investigate the role of IL-17, a cytokine that acts synergistically with IL-6, in COVID-19 pathogenesis." (PMID 41184328, 2025). "The incidence of HT among COVID-19 patients has sparked renewed interest among researchers, as these patients produce an excess of inflammatory cytokines (IL-6, IL-1β, IFN-γ, TNF-α)." (PMID 40584613, 2025). "IL-6 is one of the proinflammatory cytokines that was shown to be upregulated within the lung cytokine storm in COVID-19 patients." (PMID 40076291, 2025). "It is known that in severe COVID-19 cases, cytokines such as TNF-α and IL-6 are released in great amounts and associated with an intense and uncontrolled inflammation called the cytokine storm." (PMID 40649826, 2025). "Our data show a >50% fall in IL-6 within 48 h of VV-ECMO in COVID-19, a response that eclipses both our bacterial sepsis cohort and the 18% decline seen with conventional COVID-19 care." (PMID 40565970, 2025). "Targeting IL-6 with specific therapies has become a potentially life-saving strategy for patients with severe COVID-19." (PMID 40881695, 2025). "The development of a cytokine storm, characterized by excessive production of cytokines such as IL-6 and poor type I IFN induction, is a hallmark of severe COVID-19." (PMID 40872762, 2025). "SNPs in the TNF-α, IL-6, IL-8, IL-10, CCL5 and CXCL6 genes have been associated with COVID-19 outcomes and with serum cytokine and chemokine levels." (PMID 40881695, 2025).
COVID-19 (continued). "One of the most significant hallmarks of severe COVID-19 is interleukin-6, which has been shown to strongly correlate with disease severity." (PMID 40431602, 2025). "This includes proinflammatory markers, such as CRP, procalcitonin and interleukin-6, highlighting the important role of systemic inflammation in COVID-19 progression." (PMID 40283188, 2025). "It has been reported that cytokine storms characterized by elevated plasma IL-1β, IL-6, and TNF cytokine levels are associated with acute sequelae of COVID-19." (PMID 40872762, 2025). "IL-6 antagonists are widely accepted as therapeutic regimens for severe COVID-19, significantly mitigating the cytokine storm." (PMID 40370439, 2025). "The impact of the ACE2 rs2074192 gene polymorphism on cytokine production (IL-1β, IL-6, IL-8, and TNF-α) is also significant and should be considered when implementing renin-angiotensin-aldosterone system targeting drugs in COVID-19 therapy." (PMID 40066463, 2025). "Among all cytokines released in the COVID-19 cytokine storm, interleukin 1 (IL-1), interleukin 6 (IL-6), TNF-α and IFN-γ are prominent." (PMID 40397955, 2025). "In another study by del Valle and colleagues, they reported that high levels of IL-6 and TNF-α were associated with low survival in patients with COVID-19." (PMID 40508859, 2025). "Multiple studies indicate that cytokine levels in COVID-19—particularly IL-6—are substantially lower than those observed in classical cytokine release syndromes." (PMID 41158128, 2025). "The high level of D-dimers, which relate to hypercoagulation, combined with elevated levels of IL-6 and CRP, which reveals sustained inflammation, is most likely associated with increased infection, sepsis, and mortality in COVID-19 patients." (PMID 40149514, 2025). "Its dysregulation correlates with various pathologies, and recent evidence implicates it in the pathogenesis of COVID-19, notably through the modulation of cytokines such as interleukin-6 (IL-6) and transforming growth factor-beta (TGF-β)." (PMID 40733568, 2025). "Among the known cytokines, IL-6 is considered one of the most important predictive markers of severity and determines the need for mechanical ventilation in patients with COVID-19." (PMID 40756075, 2025). "The elevation of IL-5, IL-6, and IL-15 in PLWH/COVID-19 mirrors previously reported cytokine signatures associated with hyperinflammation and adverse clinical outcomes in both infections." (PMID 41516165, 2025). "In the current study, we found that serum IL-6, IL-10, and IL-6/IL-10 ratio were significantly higher in COVID-19 patients than controls." (PMID 41203712, 2025). "The most influential variables across the top 10 models included telomere length, HbA1c, vitamin D3, waist circumference, ApoA1, C peptide, ApoB, COVID-19 severity, duration of T2D, IL-6, cholesterol, BMI, and age." (PMID 40950970, 2025). "Prior research has correlated miR-21 upregulation with IL-6-driven cytokine storms and endothelial damage in COVID-19." (PMID 40733568, 2025). "Creatinine, D-dimer, and CRP were positively correlated with clinical outcome of female COVID-19 and IL-6." (PMID 40868247, 2025). "Neutrophil count, monocyte count, NLR, MLR, SII, CRP, CK-MB, GLU and IL-6 levels were positively correlated with COVID-19 and PD." (PMID 40292283, 2025). "Peripheral blood levels of CCL5 were found to become elevated before IL-6 in severe COVID-19 patients." (PMID 40362649, 2025). "SARS-CoV-2 did not induce significant IFN-α response or secretion of proinflammatory cytokines in the serum in the adult COVID-19 patients though the levels of IL-6, IL-8, IL-17, and IL-10 moderately increased." (PMID 39967737, 2025). "Our model predicted that both cancer and immunosuppressed virtual patients with severe COVID-19 had decreased CD8 + T cells, elevated interleukin-6 concentrations, and delayed type I interferon peaks compared to those with mild COVID-19 outcomes." (PMID 40489562, 2025).
COVID-19 (continued). "Clinical studies have identified elevated concentrations of pro-inflammatory factors, particularly TNF-α and IL-6, in the serum of COVID-19 patients." (PMID 39962185, 2025). "Given the persistence of IL-6 pathway activation in convalescent COVID-19 patients, their potential application in Long COVID is currently under investigation." (PMID 40507911, 2025). "Numerous studies have reported increased serum levels of IL-6 in COVID-19 patients, with its release significantly amplified by IL-1β and TNF-α during early inflammation." (PMID 40219044, 2025). "IL-6 levels are markedly increased in severe COVID-19 and are also chronically elevated in IPF patients." (PMID 40806851, 2025). "Anecdotal reports of anti-IL6 antibody monoclonal antibodies rescuing patients demonstrate the potential for controlling the COVID-19-induced cytokine storm during infection." (PMID 40895261, 2025). "The volcano plot identified that the patients with moderate COVID-19 exhibited significantly elevated IL-6 and sULBP2 levels." (PMID 40421029, 2025). "We further highlight clinical evidence linking IL-6 to thrombotic complications in cardiovascular disease and infection (e.g., COVID-19 and sepsis)." (PMID 40497942, 2025). "This has been coupled with numerous other studies finding that COVID-19 patients had elevated IL-6 expression and decreased lymphocyte counts." (PMID 39802655, 2025). "As we have already mentioned, biomarkers such as CRP, D-dimer, and IL-6 are clear predictive markers and have been used in clinical care for some time, since they are significantly expressed in patients hospitalized with COVID-19." (PMID 39859366, 2025). "Inflammatory and coagulation biomarkers, including D-dimer, C-reactive protein (CRP), ferritin, interleukin-6 (IL-6), and procalcitonin, are routinely measured in moderate–severe COVID-19 and frequently inform clinical decision-making." (PMID 41463074, 2025). "This is similar to a previous study in patients with ARDS from COVID-19, which demonstrated a correlation of 0.46 between IL-6 and CRP." (PMID 39969178, 2025). "At the same time, COVID-19 can activate the immune system, leading to the production of a range of cytokines such as interleukin-6 (IL-6) and tumor necrosis factor-alpha (TNF-α), which induce insulin resistance and hyperglycemia." (PMID 40046873, 2025). "Longitudinal studies have shown that cytokines such as IL-6 and IL-10 can also be used as markers of liver injury severity in patients with COVID-19." (PMID 41002992, 2025). "Specific IL-1 and IL-6 inhibitors (anakinra or tocilizumab) can be used in the treatment of severe COVID-19 complicated with respiratory failure." (PMID 40978940, 2025). "In conclusion, NLR and IL-6 represent important biomarkers for predicting AKI in COVID-19 patients, particularly in those with pre-existing CKD." (PMID 40430148, 2025). "Although the observed levels of IL-6 in severe COVID-19 are lower than in septic shock or the hyper-inflammatory response, its involvement in the regional inflammation in the pathogenicity of COVID-19 has been supported by the literature data." (PMID 40005354, 2025). "IL-6 inhibitors like tocilizumab have been extensively studied for their role in reducing cytokine storms in severe COVID-19 cases." (PMID 40794529, 2025). "These biomarkers, along with high levels of IL-1β, IL-6, TNF-α, hsCRP, and procalcitonin, are associated with increased severity and mortality in COVID-19 cases." (PMID 39967675, 2025). "A meta-analysis of 77 prospective or retrospective cohort studies in adult patients with COVID-19 showed that IL-1β, IL-2R, IL-4, IL-6, IL-8, IL-10, and IL-17, inflammatory markers, were potential risk factors for severe SARS-CoV-2 infection or mortality." (PMID 40066463, 2025). "Our study observed a significant correlation between IL-6 and fibrinogen exclusively in non-COVID-19 patients, supporting this mechanism in that group." (PMID 40364223, 2025).